CD34 (CD34 molecule)
Diseases named in the same sentence as CD34 in open-access papers (continued):
Sharing a sentence is not in itself a finding about the gene and the disease.
neuroblastoma (15 papers, 2009 to 2025). Neuroblastoma (NB) is the most common solid, extracranial childhood tumor. "The study by Natarajan Aravindan and colleagues aimed to investigate the role of CD34+ cancer stem cells (CSCs) in high-risk neuroblastoma (HR-NB) patients." (PMID 37241170, 2023). "In this case, neither material was optimum for enhancing the expression of the endothelial markers CD31/PECAM or CD34 and, therefore, endothelial transdifferentiation of monocultures of neuroblastoma cells." (PMID 39872066, 2024). "Widely used methods for PBPC purging in neuroblastoma are positive selection of CD34+ and tumour cell removal using immunomagnetic beads." (PMID 31217534, 2019). "None of the other markers tested (e.g. CD99, CD38, CD19, CD20, CyCD79a, CD34, numyogenin, nuMYOD1) was expressed by neuroblastoma cells." (PMID 23472067, 2013). "We surveyed a panel of neuroblastoma cell lines for subpopulations by assessment of stem cell marker (CD34, CD133, Nestin) expression, the presence of a verapamil sensitive side population and the ability to form clonal spheres." (PMID 19156211, 2009). "Other studies revealed that neuroblastoma cells express neural precursor markers including CD34, ABCG2, and nestin." (PMID 19156211, 2009). "Thus, CD34 has been also utilized as a biomarker to assess angiogenesis in malignancies and an increased number of CD34 surface-expressing cells has been correlated with disease progression and therapy resistance in neuroblastoma." (PMID 38069002, 2023). "These phenotypes contrasted with that of CD56++ GD2++ CD10− CD34− CD271−/+ neuroblastoma cells, which allows clear cut identification of neoplastic cells and their discrimination from normal stromal cells in BM, even when BM disseminated NBL cells were present at very low levels (data not shown)." (PMID 34638431, 2021). "Using magnetic activated sorting of CD34+ PBPCs, which is the most widely used method for PBPC purging in high-risk neuroblastoma, tumor cell depletions rates ranging from 2 log to 4.6 log were reported in different studies for tumor cell lines and clinical samples, respectively." (PMID 34654486, 2021). "The neural progenitor markers Nestin and CD34 are also expressed in neuroblastoma cells." (PMID 24116151, 2013). "Arg-1 in neuroblastoma hindered myeloid activation and suppressed CD34+ bone marrow progenitor cell proliferation, suggesting that arginine deprivation contributes to MDSC induction in neuroblastoma." (PMID 38087370, 2023). "One such model is orthotopic patient-derived xenograft (O-PDX) for neuroblastoma, in which MISTRG mice undergo double transplantation of CD34+ HSPCs and neuroblastoma xenografts." (PMID 33968039, 2021). "When PBPCs were spiked with 10% neuroblastoma cells, recoveries of up to 98% were achieved for PDX cells while more than 90% of CD34+ stem and progenitor cells were retained in the graft." (PMID 34654486, 2021). "At clinically relevant tumor cell contamination rates (0.1 and 0.01% PDX cells in PBPCs), neuroblastoma cells were depleted by more than 2-log as indicated by RT-PCR analysis of PHOX2B, TH and DDC genes, while > 85% of CD34+ cells could be retained in the graft." (PMID 34654486, 2021).
oligodendroglioma (15 papers, 2013 to 2026). A well-differentiated (WHO grade II), diffusely infiltrating neuroglial tumor, typically located in the cerebral hemispheres. "It is notable for the presence of oligodendroglioma-like cellular components, CD34 immunopositivity, and an association with cortical dysplasia." (PMID 37462746, 2023). "In fact, the diagnosis of PLNTY relies on the following essential criteria: “diffuse growth pattern and oligodendroglioma-like component and few (if any) mitotic figures and regional CD34 expression and IDH-wild type status and BRAF V600E mutation or FGFR2 or 3 fusions”." (PMID 36647073, 2023). "Histologically, the tumor showed oligodendroglioma-like morphology, strong CD34 immunopositivity, consistent with PLNTY-like features, but indicated a high proliferative index." (PMID 41798681, 2026). "Histologically, PLNTY exhibits polymorphous glial architecture with oligodendroglioma-like areas, perivascular rosettes, calcification, and diffuse CD34 positivity." (PMID 41024929, 2025). "It displays frequent oligodendroglioma-like components, calcifications, CD34 immunoreactivity, and a unique DNA methylation profile." (PMID 38730596, 2024). "PLNTY is notable for the presence of oligodendroglioma-like cellular components and CD34 immunopositivity." (PMID 36894761, 2023). "Among them, case #11 was initially diagnosed as PLNTY because the tumor presented a diffuse growth pattern with an oligodendroglioma‐like component, few mitotic figures, and CD34 extravascular immunopositivity." (PMID 37349135, 2023). "The pathological features of PLNTY were also gradually identified, namely, polymorphous appearance, the presence of oligodendroglioma-like cellular components, infiltrative growth pattern, and intense CD34 immunopositivity." (PMID 35372027, 2022). "Pathologically, the most evident morphological feature of PLNTY is infiltrative growth pattern with a mass of oligodendroglioma-like cellular components, and intense immunohistochemical staining with CD34." (PMID 35372027, 2022). "We show that PLNTYs, while morphologically variable, are uniformly characterized by the presence of oligodendroglioma-like cellular components, infiltrative growth patterns, and intense CD34 immunopositivity." (PMID 27812792, 2017). "Characteristic microscopic findings most notably include infiltrative growth, the invariable presence of oligodendroglioma-like cellular components, and intense immunolabeling for cluster of differentiation 34 (CD34)." (PMID 27812792, 2017). "However, all tumors were characterized by the presence of oligodendroglioma-like components, infiltrative growth patterns, and intense CD34 expression by tumor cells." (PMID 29701169, 2018). "Immunohistochemical markers such as CD34 are other valuable tools that can readily discriminate between PLNTY and oligodendroglioma since the last staining negatively while PLNTY stains positively." (PMID 36894761, 2023). "Except for the expression of CD34, GAFP positivity is usually seen in PLNTY and Olig-2, which indicates the neuroepithelial origin of the tumor and the oligodendroglioma-like components within the tumor." (PMID 35372027, 2022). "However, CD34 is particularly useful in differentiating PLNTY from oligodendrogliomas, which are CD34-negative." (PMID 40861626, 2025). "On the other hand, the expression of CD34 is a useful tool that can readily discriminate PLNTY and oligodendroglioma, as CD34 is present in PLNTY and absent in oligodendroglioma." (PMID 35372027, 2022).
skin cancer (15 papers, 2013 to 2026). "In vivo study observed that in utero exposure to arsenite in mice led to disrupted homeostasis of skin stem cell and increased risk of skin tumors with an accumulation of skin cancer stem cells as marked by CD34." (PMID 29081891, 2017). "However, another stem cell marker associated with skin cancer, Cd34, was upregulated comparing dorsal and tail normal skin but downregulated when lesions were compared to normal or the aggressive dorsal lesion to the more benign tail lesion." (PMID 25474466, 2014). "The capability of As3+ in inducing CSCs was first implicated in studies using in utero As3+ exposure in mice by Waalkes and colleagues, which showed that fetal exposure to As3+ enhanced the susceptibility and aggressiveness of skin tumors with an increased number of CD34+ cells, the tentative CSCs." (PMID 24675390, 2014). "A previous case report detailed the finding of a KHDRBS1-NTRK3 rearrangement found in a congenital CD34+ skin tumour." (PMID 36910630, 2023). "Bulge HF‐SCs are an important stem cell population for wound healing and for the initiation and maintenance of skin carcinomas, and are characterized by the expression of K15 and the surface marker CD34 in mice." (PMID 31556482, 2019). "When mice were administered the DMBA skin carcinogenesis protocol while overexpressing VEGF, the resulting skin tumors were more aggressive and the stemness profile of CD34+ CSCs was qualitatively altered compared to wild-type mice." (PMID 28219480, 2017). "We found CD34+ cells in the proliferative compartment (bordering the stroma) of chemically induced skin tumors of haired mice." (PMID 27409834, 2016). "Unexpectedly, we did find CD34 expression in the skin tumors from hairless mice, albeit aberrantly with a granular pattern in the differentiated cells; evidently not marking any tumor stem cells." (PMID 27409834, 2016). "Actually, K15+ bulge cells (overlapping CD34+ cells) were shown by lineage tracing to drive the growth of chemically induced skin tumors." (PMID 27409834, 2016). "The origin of CD34-positive fibroblasts in reticular dermis and partially in periadnexal dermis remains a subject of investigation, and further studies are needed to elucidate their role in skin cancers completely." (PMID 41597444, 2026). "But despite the absence of CD34+ bulge cells, hairless mice are susceptible to chemically induced skin tumors." (PMID 27409834, 2016). "Stem cell markers, CD34 and Sox2, are known to be expressed in chemically induced skin tumors." (PMID 27409834, 2016). "The development of chemically induced skin tumors is impaired in CD34-null epidermis." (PMID 27409834, 2016). "However, the role of cancer cells with high CD34 expression in UV-induced skin cancer is unknown." (PMID 33123267, 2020). "An Oncomine database analysis also demonstrated that VEGF-C expression was positively correlated with the expression of some CSC markers, such as OCT4, KLF4, NANOG, CD44, CD34 and CD133, suggesting that VEGF-C increases the CSC features of skin cancer cells." (PMID 27901498, 2017). "Therefore, we examined whether VEGF-C affects cancer stemness in skin cancer cells and found that knockdown of VEGF-C significantly decreased the expression of the CSC markers SOX2, OCT4, KLF4, NANOG, CD133, CD34 and CD44 as well as ALDH activity, which is a hallmark of CSCs." (PMID 27901498, 2017). "Another recent study showed that CD34-expressing (a carcinoma stem cell (CSC) marker) cells, residing in DMBA/TPA-induced skin tumors, formed secondary tumors upon transplantation into immunodeficient mice." (PMID 25013928, 2014). "Whether CD34 and α6-integrin expression can be considered a cancer stem cells marker in UV-induced skin cancer has not yet been investigated." (PMID 33123267, 2020).
thalassemia (15 papers, 2016 to 2026). An inherited blood disorder characterized by a decreased synthesis of one of the polypeptide chains that form hemoglobin. "Two vectors have been used for additive gene therapy in thalassemia, including betibeglogeneautotemcel, which contains autologous CD34+ hematopoietic stem cells and progenitor cells transduced with the BB305 lentiviral vector encoding beta-globin (βA-T87Q)." (PMID 39598110, 2024). "Initial reports on T-cell-depleted CD34 donation showed a 27% graft rejection rate and low thalassemia-free survival." (PMID 39598110, 2024). "We then co-transfected primary human CD34+ cells, obtained from normal, non-thalassemia controls, with pairs of CRISPR plasmids." (PMID 28871148, 2017). "Here we demonstrate the use of CRISPR/Cas9 genome editing of primary human hematopoietic stem/progenitor (CD34+) cells to emulate a natural mutation, which deletes the MCS-R2 α-globin enhancer and causes α-thalassemia." (PMID 28871148, 2017). "We initially asked whether both GGHI/VSVG and GGHI-mB-3D/VSVG γ-globin vectors, previously tested on CD34+ cells from thalassemia patients, could increase the Aγ/α ratio in SCD patients as well." (PMID 36560719, 2022). "In vitro CD34+ hematopoietic progenitor cells’ culture and flow cytometry analysis were conducted to investigate the erythroid maturation and mitochondrial clearance in β0-thalassemia/HbE erythroid cells as compared to normal cells." (PMID 35407362, 2022). "The gene-corrected human thalassemia CD34+ cells were transplanted into NSG mice." (PMID 34658870, 2021). "This resulted in the reduction of ROS to background level and improved ED/expansion of thalassemia and SCD CD34+ cells; it also suggests that the in vivo base editing could be curative in patients with β-thalassemia and SCD." (PMID 36006707, 2022). "In the absence of β-YAC mice with a thalassemia or SCD genotype or phenotype, we tested disease correction using CD34+ cells from patients with β-thalassemia and SCD." (PMID 36006707, 2022).
epithelioid hemangioendothelioma (14 papers, 2010 to 2025). A low-grade malignant blood vessel neoplasm. "Immunostaining is positive for CD31, CD34, FLI-1, AE1/AE3, and CK7, diagnostic of primary epithelioid angiosarcoma." (PMID 32983683, 2020). "To date, CD34, CD31, and ERG are the most frequently used endothelial markers for epithelioid angiosarcoma, as demonstrated by immunohistochemistry." (PMID 39958141, 2025). "There was positivity for ERG, CD34, CD31, factor VIII, and c-myc, confirming the diagnosis of an epithelioid angiosarcoma." (PMID 39958141, 2025). "A primary endovascular EHE pulmonary endovascular epithelioid hemangioendothelioma was diagnosed by endovascular biopsy with positive stains for molecular CD31, CD34 and CAMTA1, and it had low proliferative capacity characterized by Ki-67 of 5%." (PMID 36800635, 2023). "Several well-established endothelial cell markers, such as CD31 (platelet endothelial cell adhesion molecular 1), CD34 (human hematopoietic progenitor cell antigen), and factor VIII-related antigen, are used to confirm epithelioid hemangioendothelioma." (PMID 23533870, 2013). "Positive staining with endothelial markers such as CD31, CD34, and Factor VIII may be helpful in differentiating epithelioid hemangioendothelioma from carcinoma." (PMID 34757619, 2023). "CD31expression has been reported to be a more specific marker of endothelial differentiation than CD34, and ERG has high sensitivity for detecting vascular differentiation, so CD31 and ERG staining may be suitable for the diagnosis of epithelioid angiosarcoma." (PMID 35310717, 2022). "Epithelioid angiosarcoma is a variant that is positive for CD31, but it is classically negative for CD34, which is another marker of endothelial differentiation." (PMID 20179806, 2010). "Given the acknowledged limitation of CD34 in terms of specificity, it is prudent to adopt a comprehensive approach that incorporates the assessment of CD34 alongside CD31, ERG, F8, and additional pertinent markers for an accurate diagnosis of epithelioid hemangioendothelioma (EHE)." (PMID 40919137, 2025). "The renal EAS is easily misdiagnosed as epithelioid hemangioendothelioma (EHE), as it could show similar characteristics in immunohistochemical staining, such as being positive for CD31, CD34, and ERG, but the results of Ki-67, WWTR1-CAMTA1, and YAP1-TFE3 might be helpful in differential diagnosis." (PMID 39687884, 2024).
liver cancer (14 papers, 2020 to 2025). An epithelial or non-epithelial malignant neoplasm that arises from the liver. "Within our project, sc-RNA seq analysis was employed to explore the heterogeneity of ECs throughout the initiation and progression of primary liver cancer, and identified a unique subset of tumor associated senescent CD34+CLDN5+ECs, which were mainly present in the tumor tissue." (PMID 39674501, 2025). "In any case, the finding that a 1000-fold lower cell number sufficiently induced tumor formation in mice strongly supports the assumption that CD34+ liver cancer cells exhibited CS/IC properties." (PMID 35562905, 2022). "Only 100 CD34+ liver CS/ICs induced liver cancer formation in NSG mice, whereas 1 × 106 CD34− liver cancer cells were needed." (PMID 35562905, 2022). "Furthermore, to investigate the correlation of CD34+CLDN5+ ECs with overall survival duration in primary liver cancer patients, mIHC were performed on tissue microarrays containing 66 primary liver cancer specimens with long-term clinical follow-up data." (PMID 39674501, 2025). "Liver cancer may derive from transformed CD34+ stem cells in the liver according to multiple studies, indicating that stem cells are not only responsible for organ regeneration and tissue repair, but also represent a potential target for carcinogenesis." (PMID 32586050, 2020). "In contrast, a subsequent study on liver cancer found that BAs levels were positively correlated with the expression levels of VEGFR-2 and CD34, that is, BAs promoted tumor angiogenesis in liver cancer." (PMID 35127481, 2021). "The CD34+CLDN5+ cells with senescent features not only predominantly exited in iCCA and cHCC-CCA patients, but also were related with the patients' survival duration of liver cancer." (PMID 39674501, 2025). "CD34 has a synergistic effect with vascular endothelial growth factor (VEGF), which together promote the angiogenesis and cell proliferation of HCC, and then lead to the metastasis of liver cancer and the formation of tumour thrombi, thus affecting the prognosis." (PMID 35293607, 2023). "Propofol can reduce the expression of PCNA, CD34, and PATK proteins in patients, thereby increasing the activity and content of transforming growth factor TGF-β1 by 12% and 20%, respectively, thereby inhibiting the proliferation rate of liver cancer cells by 10% through the Smad2 signaling pathway." (PMID 34323647, 2021).
myxoma (14 papers, 2014 to 2025). A benign soft tissue neoplasm characterized by the presence of spindle and stellate cells, lobulated growth pattern, and myxoid stroma formation. "Immunohistochemically, all cellular myxomas (20/20, 100%) and all MFSs (9/9, 100%) showed multifocal positivity for CD34." (PMID 38791144, 2024). "Myxoma is often immunohistochemically CD34-positive, rarely SMA-positive, and desmin- and S100-negative." (PMID 39410565, 2024). "Myxomas show a diffuse positive reaction for the immunohistochemical marker Vimentin and focal expression of CD34, CD68, and SMA." (PMID 26509093, 2015). "In addition, low-grade myxofibrosarcoma (MFS) and cellular myxoma cannot be separated via immunohistochemistry, as common CD34 expression is seen in both tumor entities." (PMID 38791144, 2024). "Diagnosing myxoma is difficult as there are no useful immunohistochemical markers to distinguish intramuscular myxomas from low-grade myxofibrosarcomas, both have an abundant myxoid matrix, and both may express the CD34 molecule." (PMID 38317844, 2024). "In the present study, the pool of isolated elements of myxomas was CD34-positive." (PMID 24959280, 2014). "Histopathological analysis confirmed the diagnosis of myxoma, with immunohistochemical staining positive for calretinin, CD31, and CD34, markers supportive of a myxomatous origin." (PMID 40630762, 2025). "Immunofluorescent examination with a cocktail of antibodies against spike SARS-CoV-2/CD34 and spike SARS-CoV-2/CD68 was performed in 2 cases out of 11 (proliferating myxoma and classic myxoma)." (PMID 37895467, 2023). "Immunohistochemistry showed positivity for CD34 and negativity for smooth muscle actin (SMA), although SMA may be focally positive in some myxomas." (PMID 40677885, 2025). "Typically, myxomas exhibit positivity for endothelial markers such as CD31, CD34, and FVIIIAg." (PMID 39735071, 2024). "Myxoma immunohistochemistry demonstrates positivity for S100, CD34 and CD31, while it is negative for markers such as WT1, D2-40 and CK5/6." (PMID 38938650, 2024). "However, myxoma contains almost no mature adipocytes, and CD34 expression in myxoma is generally only focally positive." (PMID 41458523, 2025). "The myxoma cells revealed positive for vimentin and CD34, but negative for S-100 and α-SMA." (PMID 38457580, 2024).